YWHAZ (tyrosine 3-monooxygenase/tryptophan 5-monooxygenase activation protein zeta)
Diseases named in the same sentence as YWHAZ in open-access papers (continued):
Sharing a sentence is not in itself a finding about the gene and the disease.
cancer (continued). "In addition to CCND1, there are several other suggested targets for miR-193b, such as YWHAZ,PLAU(aka uPA), and KITin different cancer types 9–16." (PMID 26129688, 2015). "MYC, a well-known eccDNA-amplified driver gene which promotes cancer cell proliferation, immortalization and cross-resistance, was identified in the most cancer types (11 of 12) with the highest EGIS, followed by CCND1 (11 of 12), H3-5 (10 of 12), YWHAZ (10 of 12) and GAPDHS (10 of 12)." (PMID 40478912, 2025). "The results of these experiments demonstrate that all cancer-associated PBRM1-BD4 missense variants impair the ability of full-length PBRM1 to increase the expression of its target genes and do not affect the expression of non-PBRM1 target genes like YWHAZ." (PMID 38460939, 2024). "We had analyzed the overexpression and poor prognostic value of YWHAZ, BRCA1, and YWHAG in BRCA, so can we reasonably speculate on developing a drug to inhibit YWHAZ, BRCA1, and YWHAG-related functions to suppress cancer progression and make patients have a good prognosis." (PMID 36673982, 2023). "For example, the expression of YWHAZ in NCM460 cells is lower than that in B2M, which is the opposite in HT29 cells, indicating the stability of reference gene expression may be changed in human normal colonic epithelial cells and cancer cells." (PMID 37853035, 2023). "Expression of YWHAZ partially coincided with the expression of miR-193a in those cancer cell lines, such that MKN45 cells showing higher expression of miR-193a also showed lowest expression of YWHAZ; while AGS cells showing modest expression of miR-193a and a relatively higher expression of YWHAZ." (PMID 33718136, 2021). "Interestingly, we found that YWHAZ were upregulated in cancer tissues compared to adjacent normal tissues." (PMID 28981108, 2017). "In addition, recent studies indicate that YWHAZ acts in concert with the TGF‐β axis to control cancer‐stromal cell interaction and epithelial–mesenchymal transition 21, 26, 51, 52, which suggests other microenvironmental factors are involved in YWHAZ‐mediated carcinogenesis and cancer progression." (PMID 30945298, 2019). "Furthermore, YWHAZ has been reported to be regulated by miRNAs or long noncoding RNAs (lncRNAs) to exert its malignant functions, which may serve as potential biomarkers for the diagnosis, prognosis and chemoresistance of several cancers." (PMID 37525284, 2023). "TAGLN2 mRNA levels were significantly lower in cancer vs normal and ARHGDIA and YWHAZ levels elevated significantly and non-significantly, respectively, in the same data set." (PMID 31043708, 2019). "Focusing on the expression characterization and immunological functions of PIK3R1 and YWHAZ, we found that PIK3R1 and YWHAZ play a non-negligible role in the maturation of T cells, a role that may also be present in a variety of cancers." (PMID 39403688, 2025). "DAVID functional annotation had selected only 4 out of 16 pathways in the A549 CD166 + EpCAM + CSC subpopulation, and 3 pathways in the A549 CD166-EpCAM– non-CSC subpopulation that were related to cancer diseases and that involved the proteins YWHAB, YWHAQ, and YWHAZ." (PMID 33670440, 2021). "Furthermore, an analysis of the relationship between infiltration estimation and gene expression in gene modules revealed that T-cell CD4+ Th1 in genes ERRFI1, ZBED5, UQCRC2, ZNF146, ABHD17A, YWHAZ, and especially PLSCR4 showed a negative correlation in nearly 40 types of cancer." (PMID 38464509, 2024).
tumor (85 papers, 2008 to 2026). "KAT2A regulates H3K79 succinylation in the promoter region of YWHAZ (encoding 14-3-3ζ) to promote YWHAZ mRNA and 14-3-3ζ expression, which prevents β-linker degradation and thus promotes tumor proliferation." (PMID 40630951, 2025). "The YWHAZ gene encodes the 14-3-3 protein, which participates in several signaling pathways by binding to ligands and plays an important role in tumor genesis and development." (PMID 36388433, 2022). "YWHAZ, encodes the 14-3-3ζ protein, which is a well-known protein involved in many signal transduction and tumor progression." (PMID 34195070, 2021). "In our study, we also found that YWHAZ amplification/overexpression associated with downregulation of innate immune responses, suggesting its involvement in tumor microenvironment remodeling." (PMID 30945298, 2019). "Immunohistochemical staining confirmed the association of YWHAZ overexpression with higher tumor stages, lymph node/vascular invasion, and mitotic activity." (PMID 30945298, 2019). "Moreover, FSCN1 is related to apoptosis-associated genes, and its expression level is positively associated with YWHAZ specifically in tumor tissues and cells with PIK3CA alterations." (PMID 34249689, 2021). "YWHAZ has been shown to directly associate with AR, to promote proliferation, migration, survival and resistance to apoptosis in PC cells, to increase in PC patient tumours as compared to benign tissue, and to positively correlate with presence of metastases in clinical tumour samples." (PMID 31043708, 2019). "YWHAZ has been reported as a crucial regulator of tumor immunity, inflammation, and apoptosis pathways." (PMID 41931065, 2026). "F. nucleatum was detected in 41.5% (17/41) tumor samples and promoted the carcinogenesis through upregulating YWHAZ." (PMID 41216129, 2025). "The FC in gene expression of each marker in tumour samples relative to healthy controls was determined using the 2− ΔΔCt method normalised to the average of 7 housekeeping genes (YWHAZ, CYC1, SDHA, TBP, GAPDH, UBC and 18s RNA)." (PMID 41034696, 2025). "We validated the involvement of YWHAZ in the ENO1-mediated tumour-protective mitophagy and drug resistance, and performed rescue assays." (PMID 39828712, 2025). "YWHAZ, also referred to as 14-3-3ζ, belongs to the 14-3-3 protein family and is a central hub protein in signal transduction pathways and tumour progression." (PMID 39828712, 2025). "YWHAZ (Tyrosine 3 monooxygenase/tryptophan 5-monooxygenase activation protein zeta or 14-3-3ζ), an important factor in signal transduction and tumor progression." (PMID 41487287, 2025). "The BCL2L1, CAV1, KDELR3 and YWHAZ expression levels were upregulated in the tumour tissues and downregulated in the healthy pancreatic tissues." (PMID 38303549, 2024). "ETS1, GSK3β, VEGFA, and YWHAZ were significantly upregulated in tumor tissues (p < 0.001), indicating their oncogenic roles in HNC progression." (PMID 39518147, 2024). "YWHAZ, a member of the 14-3-3 protein family, is involved in many signal transduction pathways and plays an important role in tumor progression." (PMID 39020380, 2024). "YWHAZ, a member of the 14-3-3 protein family, functions as a central hub protein in various signal transduction pathways and plays a critical role in tumor progression." (PMID 39335311, 2024). "As for YWHAZ, IHC detection confirmed that YWHAZ was upregulated in tumour samples compared to normal ones." (PMID 38303549, 2024). "qRT‐PCR analyses revealed that the KDELR3 and YWHAZ in tumour samples were significantly higher than those in non‐cancerous samples." (PMID 38303549, 2024). "The expression of YWHAZ was lower in tumor tissues of the miR-185-5p group than in the miR-NC group." (PMID 37525284, 2023). "MiR-185-5p was down-regulated in NSCLC, and that overexpressed miR-185-5p inhibited malignant behaviors of cells and tumor growth by negatively regulating YWHAZ." (PMID 37525284, 2023).
tumor (continued). "The results showed that miR-185-5p inhibited YWHAZ expression in tumor tissues, which was in line with the results of previous cell tests." (PMID 37525284, 2023). "As a central protein involved in many signal transduction pathways, YWHAZ plays a key role in tumor progression." (PMID 37525284, 2023). "The expression level of YWHAZ in tumor tissues of small xenograft tumor model was detected by immunohistochemistry assay." (PMID 37525284, 2023). "In summary, miR-185-5p was significantly down-regulated in NSCLC, and that the overexpression of miR-185-5p inhibited malignant behaviors of cells and tumor growth by negatively regulating YWHAZ." (PMID 37525284, 2023). "The in vivo results were consistent with the in vitro results, which showed that miR-185-5p overexpression negatively regulated the expression of YWHAZ and inhibited tumor growth." (PMID 37525284, 2023). "Tyrosine 3 monooxygenase/tryptophan 5-monooxygenase activation protein zeta (YWHAZ, also named 14-3-3ζ) was identified as a central hub protein for several transduction pathways, with a significant role in tumor progression." (PMID 35512017, 2022). "The YWHAZ protein plays an important role in tumor progression and is involved in many signal transduction pathways." (PMID 36388433, 2022). "The results showed that increased CDC42, CDH2, ERBB2, JAG1, YAP1, and YWHAZ were found in the tumor tissues." (PMID 35340237, 2022). "As expected, IHC analysis revealed that both PXN and YWHAZ were notably upregulated in HCC tumor specimens in contrast with normal peritumoral tissues." (PMID 34977001, 2021). "Immunohistochemical staining confirmed that the overexpression of YWHAZ is related to higher tumor stage, lymph node/vascular infiltration and mitotic activity." (PMID 35174173, 2021). "Our study also reveals that FSCN1 expression is correlated with the expression of YWHAZ, which encodes the 14-3-3ζ protein, and that silencing FSCN1 downregulates YWHAZ only in tumor cells with PIK3CA alterations." (PMID 34249689, 2021). "YWHAZ is a central hub protein involved in many signal transduction pathways and plays a key role in tumor progression." (PMID 34035373, 2021). "Overexpression of YWHAZ is proved to be an independent prognostic biomarker for shorter disease-free survival and knockdown of YWHAZ expression by siRNA in BrCa cells significantly inhibits the tumor progression in vitro and in vivo." (PMID 34453038, 2021). "Our studies demonstrated the direct relationships among SNHG12, HuR and YWHAZ, which provides new evidence for improving tumor therapy and diagnosis." (PMID 34195070, 2021). "Herein, we demonstrated that ITGB1 enhanced HCC tumor progression via PXN/YWHAZ/AKT signaling pathways, which confers an increased growth ability to HCC tumors." (PMID 34977001, 2021). "Noteworthy, YWHAZ, which is a central hub protein regulating multiple biological processes, was also predicted to be implicated in ITGB1-mediated HCC tumor growth, based on our comprehensive analysis." (PMID 34977001, 2021). "As a novel partner of DAAM1, YWHAZ has been demonstrated to highly express in BrCa tissues and regulate the malignant phenotypes of tumor cells." (PMID 34453038, 2021). "In this study, we show that SNHG12 binds to HuR to target ELAVL1 and YWHAZ, both of which are established tumor progression-related genes, and promotes GC cell proliferation via the YWHAZ/AKT/GSK-3β axis." (PMID 34195070, 2021). "YWHAZ (also named 14-3-3ζ) is a central hub protein for many signal transduction pathways and plays a significant role in tumor progression." (PMID 32127952, 2020). "There was higher expression of TRIP13 in CRC, and TRIP13 interacted with YWHAZ, which mediates G2-M transition and epithelial-mesenchymal transition to promote tumor growth." (PMID 33193642, 2020). "At present, YWHAZ targeting therapy alone through siRNA, shRNA or miRNA to delay tumor development shows some preliminary results." (PMID 32127952, 2020).
tumor (continued). "Conversely, delayed tumor onset and reduced tumor growth were observed in mice injected with YWHAZ siRNA-treated cells compared with siRNA-control cells." (PMID 32127952, 2020). "Studies have found that YWHAZ have a vital function in tumor migration, inhibited apoptosis and regulated signal transduction." (PMID 31640760, 2019). "In a previous study, we verified that miR-451 is aberrantly down-regulated in AML patients, and it functions as a tumor suppressor through promoting cell apoptosis and inhibiting cell proliferation via targeting to and down-regulating YWHAZ in AML." (PMID 28903433, 2017). "Moreover, we performed an immunohistochemistry assay to assess the YWHAZ expression in tumor tissues." (PMID 37525284, 2023). "These evidences suggested YWHAZ played a key part in tumor progression." (PMID 35168653, 2022). "In HCC, YWHAZ downregulation could also impede the progression of the proliferation and migration of tumor cells." (PMID 35340237, 2022). "In addition, it was shown in HCC cell lines that MIR4435-2HG facilitated tumor proliferation and metastasis by modulating miR-22-3p/YWHAZ signaling." (PMID 35887228, 2022). "In conclusion, this study suggests that miR-375-3p functions as a tumor suppressor which could inhibit the progression of HCC via targeting YWHAZ and CDC42." (PMID 35340237, 2022). "Transcriptional suppression of miR-193a may led to overexpression of YWHAZ resulting in tumor progression." (PMID 33718136, 2021). "Furthermore, bioinformatics analysis revealed that paxillin (PXN) and 14-3-3 protein zeta (YWHAZ) are the molecules participating in ITGB1-regulated HCC tumor cell cycle progression." (PMID 34977001, 2021). "In this regard, epigenetic silencing of miR-193a could result in upregulation of YWHAZ and tumor invasion in vitro and in vivo." (PMID 33718136, 2021). "YWHAZ (also named 14-3-3ζ) is reported to be a central hub protein in tumor progression." (PMID 33718221, 2021). "Moreover, the positive correlation of DAAM1 and YWHAZ was observed not only in BrCa tissues but in most tumor and normal tissues." (PMID 34453038, 2021). "Tyrosine 3 monooxygenase/tryptophan 5-monooxygenase activation protein zeta (also named 14-3-3ζ or YWHAZ), belonging to the 14-3-3 protein family, is a central hub protein involved in many signal transduction pathways and plays a key role in tumor progression 1, 2, 5-8." (PMID 32127952, 2020). "Moreover, tumorigenicity was suppressed in tumor-bearing BALB/c nude mice following the YWHAZ knockdown." (PMID 31240215, 2019). "Our data indicate a correlation between YWHAZ upregulation and tumor staging." (PMID 30945298, 2019). "Circ‐SERPINE2 knockdown inhibited tumour growth of GC via regulation miR‐375/YWHAZ in vivo." (PMID 31199037, 2019). "YWHAZ, also named 14-3-3ζ, plays key roles in cell cycle and EMT16, recent researches indicated that YWHAZ involves in tumor progression and could be a prognostic marker for kinds of cancers." (PMID 29540729, 2018). "Taken together, these data demonstrate that miR-22 exhibits tumor-suppressive effects in HCC cells by regulating YWHAZ/AKT/FOXO3a signaling and might be used as an independent prognostic indicator for HCC patients." (PMID 27811373, 2016). "YWHAZ Tyrosine 3-Monooxygenase/Tryptophan 5-Monooxygenase Activation Protein, Zeta Polypeptide belongs to the 14-3-3 family of proteins which mediate signal transduction and has been suggested as having pivotal role in tumour cell proliferation." (PMID 25148247, 2014). "Furthermore, upregulation of YWHAZ is also highly related to tumor progression." (PMID 35507843, 2022). "Among these, seven genes, namely, RRM2, KIF11, ANLN, CDC20, YWHAZ, DTL, and PCNA, exhibited significantly elevated expression in tumor samples (p ≤ 0.05)." (PMID 41487287, 2025). "All three upregulated genes showed significantly increased expression in tumor tissues, with fold changes of 4.2 (RFC2, p=0.007), 3.7 (HSP90AB1, p=0.011), and 3.4 (YWHAZ, p=0.015), respectively." (PMID 41164201, 2025).
tumor (continued). "Seven GRPGs (PIM2, PGK1, ADPGK, YWHAZ, PTK2, PGAM1, and VDAC1) were significantly upregulated in the TCGA-BRCA tumor tissues." (PMID 40046063, 2025). "All 30 DEPs were significantly correlated with DDOST in 179 PAAD tumor tissue samples, among which 22 were strong correlations, including RPN2, SERBP1, CALU, STT3B, YWHAZ and MAPK1." (PMID 39223141, 2024). "miR-451a is recorded as tumor suppressor in HCC cases in many previous studies, because it significantly inhibits tumor progression via YWHAZ gene to control the growth and spread of HCC through many targets." (PMID 37168369, 2023). "Altogether, our study showed that the ITGB1/PXN/YWHAZ/protein kinase B (AKT) axis enhances HCC progression by accelerating the cell cycle process, which offers a promising approach to halt HCC tumor growth." (PMID 34977001, 2021). "In addition, six genes, KRT18, ARPC5L, ACTG1, ARPC2, EZR, and YWHAZ, were simultaneously enriched in tumors and tumor tissues highly expressing TNFRSF11B, which may enhance pathogenic E. coli focal adhesion, actin filament binding, and cadherin binding, as demonstrated by GO functional analysis." (PMID 34938284, 2021). "By analysing the TPM of YWHAZ and BCEN1 gene via GEPIA public database, we found that their expression levels were concomitantly higher in HCC tumours (n = 369) than that in non‐tumours (n = 160)." (PMID 31709727, 2020). "As a tumor-suppressive and highly abundant hepatic miRNA, miR-22 suppressed migration and invasion of HCC cells via directly targeting YWHAZ." (PMID 27811373, 2016). "As a tumor suppressor, miR-22 was proved to attenuate cell proliferation, migration and invasion of HCC cells via directly inhibiting YWHAZ expression." (PMID 27811373, 2016). "As an important tumor-suppressing transcription factor, the activity of FOXO3a can be inhibited by the cooperation between AKT and YWHAZ." (PMID 27811373, 2016). "YWHAZ modulates the activation of the AKT signaling pathway by interacting with several upstream molecules, thus enhancing AKT pathway activity and promoting tumor cell proliferation and survival." (PMID 40617805, 2025). "In addition, GSE29044 had more differentially expressed GRPGs between normal and tumor tissues (CS, PGK1, HNRNPA1, ADPGK, YWHAZ, PTK2, and PGAM1) than GSE42568 (CS, HNRNPA1, ADPGK, and PTK2)." (PMID 40046063, 2025). "We speculated that miR-185-5p plays a tumor-suppressive role in NSCLC and miR-185-5p/YWHAZ axis was involved in NSCLC progression." (PMID 37525284, 2023). "We found that hsa-miR-28-5p could partially reverse the YWHAZ-induced oncogenic effects on DLBCL cells, which was consistent with the previously discovered tumor suppressive roles of hsa-miR-28-5p in other tumors." (PMID 35027933, 2022). "Besides, compared with para-tumor tissues, the expression levels of DAAM1 and YWHAZ were both upregulated in BrCa tissues, which was in accord with previous research." (PMID 34453038, 2021). "In addition, YWHAZ and YWHAQ were also selected for further analysis since these CB-NK proteins were identified either in 1°MM or 2°MM cells and are involved in tumor cell survival." (PMID 31619273, 2019). "Organs from an egg without a tumor were used to test eight primers for cross‐reactivity with the chicken cells, namely B2M, HMBS, ALTB, TBP, SDHA, YWHAZ, and UBC." (PMID 40443053, 2025). "Further, in-depth analysis of TCGA-PRAD data revealed significantly higher gene expression profiles for SLC12A2 (P = 0.025), DDAH1 (P < 0.0001), NDRG1 (P = 0.0013), APOE (P < 0.0001), YWHAZ (P = 0.0385), and GDF15 (P < 0.0001), in PCa tumor tissue compared with non-tumoral adjacent tissue." (PMID 33483585, 2021).